HMGB1 (high mobility group box 1)
Diseases named in the same sentence as HMGB1 in open-access papers (continued):
Sharing a sentence is not in itself a finding about the gene and the disease.
Sepsis (continued). "Further in vitro experimental data suggested that SGC-CBP30 exerted its therapeutic effects on sepsis by inhibiting the LPS-induced transcriptional output of HMGB1 and its release from THP-1 cells and MPM cells." (PMID 33603756, 2020). "In an animal model of sepsis, expression levels of HMGB1 mRNA in the liver, lungs, kidneys, and small intestine of rats were markedly increased." (PMID 32796569, 2020). "A growing number of in vivo and in vitro investigations reveal that HMGB1 plays a pivotal role in the processes of inflammatory response and immunosuppression of sepsis." (PMID 33552058, 2020). "The administration of HMGB1 antagonist in the late stage of animal sepsis model can improve the survival rate, and the intensity of inflammatory response in HMGB1 knockout mice is significantly reduced." (PMID 32153412, 2020). "This review of herbal extracts has identified multiple candidates which can target the release of HMGB1 and potentially reduce mortality by preventing progression from respiratory distress to sepsis." (PMID 32629817, 2020). "Dynamic monitoring indexes of HMGB1 and cellular immunity are vital for assessing chronic inflammation processes, immune status, and prognoses of patients with severe sepsis." (PMID 33552058, 2020). "It has been well proven that systemic HMGB1 levels are markedly increased in murine sepsis models and in patients with sepsis." (PMID 33552058, 2020). "Taken together, these results suggested that toddalolactone protects LPS-induced sepsis and attenuates LPS-induced inflammatory response by modulating HMGB1-NF-kB translocation." (PMID 32153412, 2020). "The delayed secretion of HMGB1 broadens the time window of treatment opportunities for patients with sepsis using HMGB1 antagonists." (PMID 33552058, 2020). "Administration of HMGB1 A box as an HMGB1 antagonist has been shown to reverse lethality in a model of sepsis." (PMID 32536928, 2020). "The intriguing clinical therapeutic correlate to each one of these identified HMGB1 antagonists is that they can be delivered with exceptional delay (up to 24 h after sepsis initiation) with beneficial effects." (PMID 32265930, 2020). "Sesamin improved the 7-day survival rate of septic mice, suppressed the inflammatory response in sepsis through the HMGB-1/TLR4/IL-33 signalling pathway, and further alleviated intestinal injury." (PMID 32893702, 2020). "HMGB1 in circulation from patients subjected to sepsis promoted ECs apoptosis, which in turn increased endothelial." (PMID 33552058, 2020). "As an effective pro-inflammatory cytokine, HMGB1 plays a role in various inflammatory diseases, especially in sepsis." (PMID 33552058, 2020). "We have previously demonstrated that hepatocytes release HMGB1 in sepsis and that this requires caspase-11 and GsdmD." (PMID 32328059, 2020). "The present study aimed to verify the protective effects of SESN2 on apoptosis of DCs under stimulation with HMGB1 and during sepsis and tried to identify the key molecules in ERS-related apoptosis signaling pathways." (PMID 32071292, 2020). "It is regrettable that there are relatively few investigations on when HMGB1 acts a pro-inflammatory or immunosuppressive effect in sepsis." (PMID 33552058, 2020). "Many reagents targeting HMGB1, its release or downstream pathways have been reported, but no drug has yet been fully developed for clinical management of sepsis." (PMID 32983116, 2020). "HMGB1 is reported to contribute to inflammatory dysfunction in sepsis and ALI, and the levels of HMGB1 in the plasma and tissue were significantly increased in a mouse model of lipopolysaccharide (LPS)-induced mouse model of ALI." (PMID 32636835, 2020). "Experimental data established HMGB1 as a late mediator of lethal endotoxemia and sepsis, with a wide–over 24 h–therapeutic window, which allows for the clinical management of lethal systemic inflammatory diseases." (PMID 32629817, 2020).
Sepsis (continued). "Emerging evidence has shown that expression of the HMGB1 gene is significantly increased during sepsis in activated immune cells and necrotic tissues 6-8." (PMID 33061810, 2020). "In this study, we have demonstrated, for the first time, that the HMGB1/PTEN/β-catenin signaling represents a novel regulatory pathway to induce CD4+CD25+Foxp3+ Tregs in sepsis-induced lung injury." (PMID 31402909, 2019). "High-mobility group box 1 protein (HMGB1), a highly conserved and ubiquitous DNA binding nuclear protein, is a key mediator during inflammatory responses in sepsis." (PMID 31402909, 2019). "Our data document that HMGB1/PTEN/β-catenin signaling is critical for development of Tregs in the resolution of sepsis-induced lung injury." (PMID 31402909, 2019). "It was previously reported that EP prevents mice lethal sepsis by inhibiting HMGB1 release from inflammatory cells." (PMID 30988279, 2019). "For example, a recent report shows that the chaperone HMGB1, both alone and together with LPS, induced pro-inflammatory responses that prevented sepsis." (PMID 30669362, 2019). "Our recent published paper showed that the main acetylated sites of HMGB1 in sepsis induced AKI is K28–30." (PMID 31333497, 2019). "The aim of our systematic review and meta-analysis is therefore to assess the prognostic value at onset of sepsis of serum Ang-1, Ang-2, HMGB1, sRAGE, sTREM-1, and suPAR, in adult patients with sepsis or septic shock." (PMID 31705327, 2019). "The present study focused on the inhibition of cerebral HMGB1 in alleviating multiple organ damage by virtue of the protective effects on sepsis-induced brain injury, thus highlighting the therapeutic value of central HMGB1 for septic response." (PMID 30881224, 2019). "Recently, the PAMP, lipopolysaccharide (LPS), in a complex with the DAMP, HMGB1, was shown to trigger pro-inflammatory signaling that was distinct from LPS treatment or HMGB1 treatment alone in the context of sepsis." (PMID 30669362, 2019). "IL-2 expression and release in CD4+ T cells was reduced under sepsis exposure, and this was reversed by inhibiting central HMGB1, especially at the dose of 10 μg BoxA." (PMID 30881224, 2019). "Prevention of ds-HMGB1/MD-2 interaction abrogates cytokine induction and protects against liver injury, chemical toxemia and sepsis." (PMID 30306212, 2019). "Clostridium species and α-hemolytic Streptococcus induce epithelial cell necrosis, which triggers the release of proinflammatory cytokines and high mobility group protein B1 (HMGB1), a well-described danger-associated molecular pattern associated with sepsis." (PMID 31272492, 2019). "HMGB1 is a mediator of systemic inflammation in sepsis and trauma, and a promising biomarker in many diseases." (PMID 31892315, 2019). "Memory impairment and brain pathology were both improved upon administration of anti-HMGB1 antibody to mice survivors beginning 1 week after onset of sepsis." (PMID 31892321, 2019). "Inhibition of extracellular HMGB1 attenuates inflammation and confers protection in several animal models of experimental diseases including sepsis, cardiac and liver ischemia/reperfusion injury, diabetes, autoimmune diseases and epilepsy." (PMID 30306212, 2019). "In systemic inflammation of sepsis, HMGB1 is a late mediator of lethality; however, HMGB1 also acts an early mediator of inflammatory responses following IR." (PMID 31072024, 2019). "GTS-21 (also known as DMBX-anabaseine) inhibits pro-inflammatory cytokines like TNF, IL-1β, IL6 and HMGB1 and improves survival in murine endotoxemia and sepsis models." (PMID 30947238, 2019). "Inhibiting the release of HMGB1 protects against severe sepsis, as shown by the alleviation of multiple organ dysfunction and the improved survival of septic animals." (PMID 30881224, 2019). "HMGB1 has been identified as an essential therapeutic target for sepsis due to its efficacy in driving an uncontrolled inflammatory response and poor outcomes." (PMID 30881224, 2019).
Sepsis (continued). "Two recent studies have also demonstrated novel findings that significantly guide our understanding of the key HMGB1/LPS-mediated molecular mechanisms operating in the pathogenesis of sepsis." (PMID 30975096, 2019). "Since DAMPs like HMGB1 also participate in septic phenomena, it should not be surprising that a state of chronic stimulation of tissue macrophages synergizes with a sepsis state of peak in HMGB1." (PMID 30766533, 2019). "EP downregulated the expression of multiple proinflammatory proteins, including IL-1β, TNF-α, and HMGB1 in animal experiments of endotoxemia and sepsis." (PMID 31933629, 2019). "The plasma of HMGB1 in healthy people (and animals) was around 5 ng/ml (0.2 mM), while in patients with sepsis, serum HMGB1 reached 150 ng/ml (6 mM)." (PMID 31929852, 2019). "Inhibition of calcium/calmodulin-dependent protein kinase Iα increased survival rate by reducing systemic concentrations of IL-10, IL-6, TNF-α, and HMGB1 in a CLP model of sepsis." (PMID 30848296, 2019). "Previous experiments have confirmed that extracellular HMGB1 is a lethal inflammatory mediator in late sepsis as it activates the inflammation-related signalling pathways by binding with its specific receptors RAGEs/TLR-2/TLR-4." (PMID 31781288, 2019). "HMGB1 is elevated in patients with sepsis, and dozens of studies have demonstrated that targeting HMBG1 improves outcomes in sepsis." (PMID 31736963, 2019). "Recent studies reported that EP markedly decreased the HMGB1 release in murine colitis, sepsis or renal IR." (PMID 31072024, 2019). "Conversely, administration of HMGB1-specific neutralizing antibodies or the HMGB1-binding antagonist thrombomodulin can rescue mice and rats from lethal sepsis." (PMID 31092889, 2019). "In the present study, we observed that HMGB1 can be induced in endotoxin-stimulated macrophages during sepsis." (PMID 31402909, 2019). "The exaggerated secretion/release of HMGB1 has a detrimental effect on surviving patients with sepsis." (PMID 31847111, 2019). "The role of the proinflammatory cytokine HMGB1 has been studied with much interest in various organ injuries and sepsis." (PMID 31771292, 2019). "In this study, we deleted the murine Gstp gene cluster and found that GSTP significantly decreased the mortality of experimental sepsis and reduced related serum level of high mobility group box-1 protein (HMGB1)." (PMID 29520271, 2018). "In a mouse model of lethal sepsis, it has been demonstrated that CQ inhibits HMGB1-mediated inflammation by blocking NF-κB activation, then improves LPS-induced lethal death in mice." (PMID 30478280, 2018). "In fact, it is well known that HMGB1 plays a key role in mediating systemic inflammation during sepsis and that high levels correlates with bad prognosis." (PMID 29791477, 2018). "Plasma and sputum HMGB1 levels did not correlate to disease severity (pneumonia severity index or presence of sepsis), but high sputum HMGB1 level was correlated to pneumococcal aetiology (p = 0.002)." (PMID 30194360, 2018). "To date, only weak correlations have been reported between cfDNA and DNA-histone-complexes in people after cardiac arrest, and between cfDNA and HMGB1 in dogs with sepsis." (PMID 29686994, 2018). "As the beneficial effect of VNS on colonic inflammation was only mild, increased survival most likely results from its effect on HMGB1 production, a key determinant of survival in sepsis." (PMID 29791477, 2018). "Previous researches have shown that HMGB1 inhibitor BoxA reversed lethality of established sepsis, decreased sepsis-induced organ injury, prevented HMGB-induced leukocyte recruit, diminished CTL-induced liver disease in HBV transgenic mice." (PMID 29520271, 2018). "Both HMGB1 and IL-1β have been found to play critical roles in sepsis and post-burn immune dysfunction." (PMID 29601597, 2018).
Sepsis (continued). "The therapeutic benefits of HMGB1 have been explored in sepsis survivors where HMGB1 mediates cognitive dysfunction in a murine model of severe sepsis survivors." (PMID 30271319, 2018). "To our knowledge, we are the first to report that nuclear GSTP functions as a negative regulator to control HMGB1 release from macrophages and decreases the mortality of sepsis." (PMID 29520271, 2018). "Previous studies identified HMGB1 as a late mediator of lethal systemic inflammation in sepsis, acting as a pro-inflammatory cytokine inversely related to survival." (PMID 29791477, 2018). "A study by Li found that EGCG protects against lethal endotoxemia and sepsis by inhibition of HMGB1." (PMID 29460131, 2018). "For example, IL-6, TNF-α, and HMGB1 levels are significantly higher in sepsis patients than in patients with other diseases or healthy people." (PMID 29780830, 2018). "Passive release occurs rapidly and hence in trauma likely reflects early tissue damage, while the active release occurs more slowly, which makes HMGB-1 a late marker in sepsis." (PMID 30105229, 2018). "The dynamics of HMGB-1 concentrations in diverse patient populations including sepsis, SIRS, pyometra, GDV, trauma, and routine surgery likely reflect a complex interplay of disease process, illness severity, clinician interventions, and measurement timing." (PMID 30105229, 2018). "HMGB1 is released during sepsis and is sufficient to recapitulate LPS-induced lethality upon injection." (PMID 29520027, 2018). "HMGB1 acts as a pro-inflammatory cytokine mediator of sepsis; however, it induces a weak tumor necrosis factor (TNF)-α production in in vitro treatments." (PMID 29696019, 2018). "The current study not only explored the source of HMGB1 that induces Mφ pyroptosis, but also validated the pathway in sepsis model." (PMID 29789550, 2018). "High mobility group box 1 (HMGB1) has been proposed as crucial in the pathogenesis of many diseases including sepsis." (PMID 29988587, 2018). "Ethyl pyruvate (EP) was previously shown to inhibit HMGB1 release and promote survival during endotoxemia and experimental sepsis." (PMID 30134814, 2018). "More recently, elevated levels of serum high-mobility group box 1 (HMGB1) was found in a murine model of sepsis and administration of anti-HMGB1 monoclonal antibodies significantly ameliorated the development of anemia." (PMID 30134792, 2018). "Accordingly, we demonstrated that the clearance rates of HSP70 and HMGB1 were higher in AKI patients with sepsis who expired." (PMID 30666251, 2018). "HMGB1 and S100A8/A9 are acutely elevated in patients presenting with sepsis and are associated with worse outcome." (PMID 30459764, 2018). "Following LBI, HMGB1 is secreted in plasma up to three weeks after the initial injury, and correlates with onset of sepsis and mortality." (PMID 29601597, 2018). "In‐depth research on HMGB1 has shown that HMGB1 is associated with TLR4‐mediated inflammatory response and a variety of diseases, such as sepsis and gliomas." (PMID 29670828, 2018). "Clinically, enhanced blood HMGB1 levels are detectable in septic patients up to 7 days after a diagnosis of sepsis, and these HMGB1 concentrations are related with the severity of organ damage and death." (PMID 29520271, 2018). "The increase of serum HMGB1 appears to be a key lethal factor in sepsis, and the control of HMGB1 is crucial in the management of sepsis." (PMID 29520271, 2018). "At ICU discharge, HMGB1 was higher and RvD5 was lower in the patients who died in the first year after sepsis compared to the survivors." (PMID 29467023, 2018). "Both the DAMP High-Motility Group Box-1 (HMGB1) and the cytokine IL-1β have been found to play critical roles in sepsis and post-burn immune dysfunction." (PMID 29601597, 2018). "Neutralization of C5a prevents breakdown of the BBB in experimental sepsis and suppression of HMGB1 release, suggesting that HMGB1-mediated complement activation is an important therapeutic target." (PMID 29696019, 2018).
Sepsis (continued). "Extracellular HMGB1 triggers inflammation and also functions as a late mediator of endotoxemia and sepsis in both animal models and human patients." (PMID 29696019, 2018). "HMGB1 is a proinflammatory mediator that contributes to the pathogenesis of many disorders, including sepsis and colitis." (PMID 30134814, 2018). "According to our review of relevant literatures, the effects of salidroside on late phase mediator of HMGB1 in severe sepsis and sepsis-induced acute lung injury models were seldom reported in these previous studies." (PMID 28931916, 2017). "The administration of anti-HMGB1 monoclonal antibody also significantly attenuated splenomegaly and splenocyte priming levels in sepsis-induced survivors." (PMID 28535799, 2017). "While approaches targeting HMGB1 have demonstrated reduced mortality in pre-clinical models of sepsis, the impact of HMGB1 blockade on the complex septic inflammatory milieu and the development of subsequent immunosuppression remain enigmatic." (PMID 28724977, 2017). "Decreased HMGB1 expression through increased HO-1 production takes a protective role in several disease states, including arthritis and sepsis." (PMID 29085368, 2017). "In an experimental rat model of sepsis caused by CLP, salidroside administration significantly attenuated lung injury and reduced the serum HMGB1 level." (PMID 29333216, 2017). "The expressions of HMGB1 in cortex, hippocampus, and striatum were significantly enhanced in the sepsis group when compared with the sham group." (PMID 29190939, 2017). "Various inflammation-associated factors, including LPS, TNF-α, IL-1, nitric monoxide, PAF, Braun’s lipoprotein (BLP), and high-mobility group box 1 protein, promote inflammation leading to sepsis." (PMID 28912777, 2017). "Our findings also reveal a significantly up regulated expression of HMGB1 in other sepsis cases compared to healthy controls." (PMID 28628607, 2017). "HMGB1 plays a critical role in sepsis-induced acute lung damage and has been identified as a late effector of sepsis lethality." (PMID 29258263, 2017). "Previous studies have found HMGB1 as an important inflammatory mediator and proinflammatory cytokine, which links in response networks of sepsis proinflammatory cytokine." (PMID 29073894, 2017). "Studies using neutralizing antibodies for HMGB1 have verified that increased circulating levels of HMGB1 contribute to the late lethality of endotoxemia and sepsis." (PMID 29085368, 2017). "In an animal sepsis model, using cecal ligation and puncture methods in mice, the administration of anti-HMGB-1 during the late stages improved survival." (PMID 28286376, 2017). "HMGB1 further plays an important role in sepsis by facilitating the transfer of LPS to CD14 to initiate a TLR4-dependent proinflammatory response." (PMID 29261777, 2017). "Interdiction of HMGB1 activity through neutralizing Abs or soluble Receptor for Advanced Glycation Endproducts is protective in multiple systems, including sepsis, endotoxemia, traumatic injury, cancer, colitis, arthritis, and infection." (PMID 28533778, 2017). "HMGB1 released from activated macrophages is an endogenous danger signal to augment inflammatory responses in sepsis." (PMID 28931916, 2017). "In future, it will be crucial to evaluate the efficacy of HMGB1‐targeting strategies for the treatment of human sepsis." (PMID 28039939, 2017). "Emerging evidences indicate that HMGB1 is an important factor that links gut BT and sepsis, and extracellular histones are also important factors that significantly contribute to MOF in ALF." (PMID 28694564, 2017). "In the late sepsis phase, salidroside protected against sepsis-induced acute lung injury through the SIRT1-mediated HMGB1 nucleocytoplasmic translocation pathway." (PMID 28931916, 2017). "1,25-Dihydroxyvitamin D plays a key role in sepsis, and HMGB1 is a late mediator of endotoxin lethality released from macrophages, so we examined the effects of 1,25(OH)2D3 on HMGB1 secretion in macrophages." (PMID 29085368, 2017).